CHRNA5 (cholinergic receptor nicotinic alpha 5 subunit)
Diseases named in the same sentence as CHRNA5 in open-access papers (continued):
Sharing a sentence is not in itself a finding about the gene and the disease.
nicotine dependence (continued). "Several studies have revealed that the CHRNA5-CHRNA3-CHRNB4 cluster of neotenic acetylcholine receptor subunit genes also have a role in nicotine dependence, and the variant in this genetic region might increase lung cancer risk through smoking." (PMID 26079375, 2015). "Here, we propose that the genetic locus of susceptibility to nicotine addiction, the CHRNA5/A3/B4 gene cluster, encoding the α5, α3 and β4 subunits of the nicotinic acetylcholine receptors (nAChRs), may influence nicotine-induced neuroadaptations." (PMID 25384568, 2014). "Therefore, the objective was to characterize the mediation effects of nicotine dependence on the relationship between genetic variants in the five nicotinic receptor genes (CHRNA5/A3/B4, CHRNB3, and CHRNA6) and lung ADC risk among ever smokers." (PMID 25233467, 2014). "In summary, our results show that genetic variants in the CHRNA5/A3/B4 region may impact lung ADC through nicotine dependence." (PMID 25233467, 2014). "Recent genome wide association studies have identified several polymorphisms within genetic loci that includes the nAChR subunit genes CHRNA5/A3/B4 (which encode the nAChR α5, α3, β4 subunit, respectively), that are associated with nicotine dependence, COPD, and lung cancer." (PMID 23641218, 2013). "In addition, genetic variation in CHRNA5, distinct from those associated with nicotine dependence, are also associated with alcohol dependence." (PMID 23641218, 2013). "Earlier efforts to identify gene polymorphisms that may lead to nicotine addiction have highlighted the CHRNA5/CHRNA3 gene cluster on chromosome 15 as a potential candidate." (PMID 22380605, 2012). "Individuals who harbour the variant of CHRNA5 (which decreases cholinergic receptor activity) may have an increased risk of nicotine dependence as higher levels of nicotine are required to achieve similar activation of the dopaminergic pathway." (PMID 21966413, 2011). "The CHRNA5 gene encodes the α5 subunit of the neuronal nicotinic acetylcholine receptor (nAChR), which can be activated by nicotine, the principal active compound among the 4000 chemicals in tobacco smoke, and plays a key role in the development of nicotine dependence." (PMID 41007821, 2025). "Indeed, both the coding polymorphism rs16969968, altering the protein structure of the α5 subunit, and the regulatory variations upstream of the initiation codon of CHRNA5 mRNA (rs503464, rs55853698, and rs55781567) were shown here to have a role in the genetic predisposition to nicotine dependence." (PMID 29196725, 2017). "Therefore, del allele homozygotes at rs3841324 are more likely to be at increased risk for nicotine dependence and smoking persistence with increased CHRNA5 mRNA levels in the frontal cortex, and is consequently more likely to be associated with a higher incidence of smoking-mediated cancers." (PMID 25329654, 2014). "It has been suggested that variants within both genes, CHRNA5 and CHRNA3, influence the nicotine use pathways, leading to the development of nicotine addiction and a reduction in smoking cessation." (PMID 38862938, 2024). "The CHRNA5/A3/B4 gene locus is closely related to nicotine dependence and other smoking-related disorders." (PMID 38021533, 2023). "Genetic factors, which are indicated in affecting nicotine dependence, include genetic variants of α3, α4 and α5 subunits of nicotinic receptors, which are encoded by CHRNA3, CHRNA4 and CHRNA5 genes, respectively." (PMID 35222535, 2022). "CHRNA5 was initially recognized as an important regulator in nicotine addiction and nicotine-dependent lung cancer development." (PMID 35214008, 2022). "The gene cluster region, CHRNA3/CHRNA5/CHRNB4, encoding for nicotinic acetylcholine receptor (nAChR) subunits, contains several genetic variants linked to nicotine addiction and brain disorders." (PMID 34206324, 2021). "More recent studies using rodent models have provided further insight into the role of Chrna5 in nicotine dependence." (PMID 34803779, 2021).
nicotine dependence (continued). "The CHRNA3/CHRNA5/CHRNB4 gene cluster, encoding for the α3, α5 and β4 nicotinic acetylcholine receptor (nAChR) subunits, has drawn interest due to its implication in nicotine dependence and lung cancer." (PMID 34206324, 2021). "Smoking has profound effects on DNA methylation, and the CHRNA5 locus has been reported to be related to nicotine addiction." (PMID 33752734, 2021). "Both the CHRNA3 and CHRNA5 genes are expressed in human brain regions relevant to nicotine addiction, such as the nucleus accumbens, amygdala, and entorhinal cortex." (PMID 31362771, 2019). "The results of the 4-SNP haplotype/diplotype analysis confirm and extend previous findings on the genetic influence of the CHRNA5-CHRNA3-CHRNB4 gene cluster on nicotine dependence and reconcile previous GWAS data." (PMID 30453884, 2018). "Of note, our findings point to the importance of the CHRNA5 regulatory SNP rs503464 in both nicotine dependence and smoking-cessation success." (PMID 29196725, 2017). "A previous study showed that single-nucleotide polymorphisms in CHRNA5 and CHRNA3 were associated with nicotine dependence." (PMID 29207642, 2017). "Genome-wide association studies (GWASs) have identified associations between the CHRNA5–CHRNA3–CHRNB4 gene cluster and smoking heaviness and nicotine dependence." (PMID 27871728, 2016). "Cluster of two genes CHRNA5 and CHRNA3 on the chromosome 15q25 region, which encodes neuronal nicotinic acetylcholine receptor subunits, is associated with nicotine dependence and smoking quantity." (PMID 27344179, 2016). "We inspected the CHRNA5-CHRNA3-CHRNB4 cluster, the CHRNA6-CHRNB3 cluster and CHRNA4, which are genes showing confirmed association to nicotine dependence and smoking behaviours." (PMID 27957625, 2016). "We previously identified common SNPs in a distant regulatory element (DRE) that increase CHRNA5 mRNA expression in the human prefrontal cortex (PFC) and confer risk for nicotine dependence." (PMID 27350810, 2015). "This study provides strong evidence for the role of the CHRNA5-CHRNA3-CHRNB4 cluster in heaviness of nicotine addiction." (PMID 25632390, 2015). "In the last several years, genetic studies of smoking and nicotine dependence have made significant progress, exemplified by the identification of the CHRNA5-CHRNA3-CHRNB4 locus." (PMID 25826680, 2015). "The CHRNA5-CHRNA3-CHRNB4 gene cluster, encoding the α5, α3, and β4 nicotinic acetylcholine receptor (nAChR) subunits, has been linked to nicotine dependence." (PMID 24478678, 2014). "Our findings are consistent with other studies that show that variations in CHRNA5/A3/B4 are significantly associated with lung ADC risk and nicotine dependence." (PMID 25233467, 2014). "Recently, variants in the nAChR genes CHRNA3, CHRNA5, and CHRNB4 have been implicated in nicotine dependence and lung cancer susceptibility." (PMID 24062692, 2013). "The CHRNA5-CHRNA3-CHRNB4 gene cluster on 15q25 has consistently been associated with smoking quantity, nicotine dependence and lung cancer." (PMID 23029550, 2012). "The CHRNA5-CHRNA3-CHRNB4 gene cluster at 15q25 has consistently been associated with smoking quantity and nicotine dependence, as well as with lung cancer and chronic obstructive pulmonary disease." (PMID 23029550, 2012). "Genome-wide association studies implicate variations in CHRNA5 and CHRNA3 as being associated with nicotine addiction (NA)." (PMID 21858091, 2011). "Extensive genotyping of the CHRNA5-CHRNA3-CHRNB4 region has provided potential evidence for at least two additional distinct signals for nicotine dependence." (PMID 20700436, 2010). "Recently, genetic findings for nicotine dependence and smoking related diseases converged to implicate the chromosome 15q25.1 region, which includes the CHRNA5-CHRNA3-CHRNB4 cluster of cholinergic nicotinic receptor subunit genes." (PMID 20700436, 2010).
nicotine dependence (continued). "In the chr15q25.1 region spanning the nicotinic receptors CHRNA3 and CHRNA5, we identified multiple SNPs associated with CPD (p<10−3), including rs1051730, which has been associated with nicotine dependence, smoking intensity and lung cancer risk." (PMID 19247474, 2009). "A wider survey of nAChR gene variants in a case-control study for nicotine dependence found evidence for nominally significant associations in CHRNA7, CHRNA9, CHRNA5 and CHRNB3 in young Israeli women." (PMID 18618000, 2008). "Additionally, two markers in CHRNA5 (rs16969968) and CYP2A6 (rs1801272) genes, associated with increased risk for nicotine dependence in smokers, were proven to be carried by the Saudis involved in our study." (PMID 40376268, 2025). "Hartz and colleagues, focusing on the nicotinic receptor subunit genes associated with nicotine dependence (CHRNA5/CHRNA3/CHRNB4 on chromosome 15q25 and CHRNB3/CHRNA6 on chromosome 8p11) investigated the relationship between nicotine dependence and bipolar disorder." (PMID 35893041, 2022). "Thus, previous studies regarding CHRNA5 have largely focused on its role in nicotine dependence and lung cancer progression." (PMID 35214008, 2022). "The CHRNA3 and CHRNA5 genes participate in the mechanism of nicotine addiction and lung damage." (PMID 33801584, 2021). "Such knowledge may lead to a better understanding of the neurobiology of Chrna5-dependent nicotine consumption as well as suggest novel therapeutic strategies for treating nicotine dependence in humans." (PMID 34803779, 2021). "Risk variant rs578776, a variant in the CHRNA5–CHRNA3–CHRNB4 gene cluster, influences susceptibility to nicotine dependence by dampening the response of the anterior cingulate cortex to reward feedback, without recruiting the striatum or orbitofrontal cortex during feedback or anticipation." (PMID 32601453, 2020). "In vitro studies indicate that rs16969968 decreases CHRNA5 function and favors nicotinic addiction." (PMID 32257438, 2020). "Genome-wide association studies (GWASs) have highlighted genetic variants in the CHRNA5–CHRNA3–CHRB4 gene cluster associated with smoking heaviness and nicotine dependence as well as known smoking-related diseases such as chronic obstructive pulmonary disease (COPD) and lung cancer." (PMID 27871728, 2016). "Our objectives were to evaluate whether previously identified genetic risks for nicotine dependence (i.e., SNPs at the CHRNA5 locus) predicted variation of self-reported subjective states using psychometric analyses with structural equation modeling." (PMID 25826680, 2015). "We previously undertook pooled sequencing of the coding regions and flanking sequence of the CHRNA5, CHRNA3, CHRNB4, CHRNA6 and CHRNB3 genes and found that rare missense variants at conserved residues in CHRNB4 are associated with reduced risk of nicotine dependence among African Americans." (PMID 24804708, 2014). "Genome-wide association studies (GWAS) have identified that chromosome 15q25.1, composed of nicotinic acetylcholine receptor genes, including CHRNA5 and CHRNA3, are lung cancer susceptibility regions and play a potential role in multiple smoking-related phenotypes and nicotine dependence." (PMID 25329654, 2014). "Several genome-wide association and candidate gene studies have linked chromosome 15q24–q25.1 (a region including the CHRNA5-CHRNA3-CHRNB4 gene cluster) with alcohol dependence, nicotine dependence and smoking-related illnesses such as lung cancer and chronic obstructive pulmonary disease." (PMID 22438940, 2012). "Additionally, we detected a significant association for two 5′-UTR polymorphisms of CHRNA5 gene (rs503464 and rs55781567) that had never been associated with nicotine dependence." (PMID 29196725, 2017).
nicotine dependence (continued). "Our primary goals were to evaluate how nicotine administration influenced subject's mood and affect as measured by the POMS, PANAS and DEN, and whether mood states and affect were influenced by genetic risks of nicotine dependence using the established markers from the CHRNA5-CHRNA3-CHRNB4 locus." (PMID 25826680, 2015). "Despite strong evidence for altered Chrna5 expression in the rodent habenula affecting addiction phenotypes, and the association of regulatory DRE SNPs with nicotine addiction, it is unknown whether the DRE SNPs affect CHRNA5 mRNA expression in the human habenula." (PMID 27350810, 2015). "We found genes related to nicotine addiction (CHRNA3, CHRNA4, CHRNA5), neurodegeneration (IREB2), chromosome maintenance (HIST1H2BD), mRNA stability (CSDC2), and transcriptional repression to be potentially affected by the pregnancy maternal smoking phenotype." (PMID 40074595, 2025). "Previously, we had reported other SNPs in smoking-related genes as NRXN1, DRD4, HTR2A, CHRNA3, CHRNA5, and CYP2A6 in Mexican mestizo, focused on smokers enrolled in a smoking cessation program, mostly with high tobacco consumption and nicotine dependence." (PMID 34205269, 2021). "Second, the neurotransmitter receptors in this pathway (including CHRNA5, CHRNA3, CHRNB4, and CHRND) participate in the biological process by which smoking induces nicotine dependence." (PMID 30104567, 2018). "Multiple distinct loci at the CHRNA5-CHRNA3-CHRNB4 locus on 15q24-25 appear to affect smoking behavior, and among multiple phenotypes describing nicotine dependence it is genetic factors that are most frequently found responsible for heaviness of smoking." (PMID 25632390, 2015). "In contrast with other studies, rs16969968 CHRNA5 SNP was not in correlation with nicotine dependence." (PMID 38862938, 2024). "In addition, several other COPD GWAS loci have strong candidate genes, such as the nicotinic acetylcholine receptor genes that have been related to nicotine addiction (CHRNA3 and CHRNA5) and TGFB2 (part of the TGFBeta pathway)." (PMID 30262855, 2018). "These initial findings renewed interest in CHRNA5 and CHRNA3 and the role played by these genes in nicotine dependence, and led on to a series of preclinical follow-up studies focused on determining the mechanism underlying the observed associations with smoking behaviour and disease." (PMID 26866486, 2016). "Three SNPs in CHRNA5 (rs6495306, rs680244 and rs621849), in complete LD (r2 = 0.99), had a significant total effect (p = 0.03, FDR q = 0.023) and direct effects (p = 0.04, FDR q = 0.034), but the indirect effect through nicotine dependence was not significant." (PMID 25233467, 2014).
lung carcinoma (82 papers, 2009 to 2025). "Increasing evidence suggests that the α5 nicotinic acetylcholine receptor (α5-nAChR), encoded by the CHRNA5 gene, is one of a key mediator involved in lung cancer development and immune responses." (PMID 40143965, 2025). "CHRNA5 (15q25.1) is localized in lung cancer susceptibility loci, and CHRNA5 polymorphism is related to lung cancer susceptibility." (PMID 35071775, 2022). "CHRNA5 encodes the α5 nicotinic acetylcholine receptor subunit and is involved in the nicotine-induced proliferation of lung cancer cells." (PMID 36389709, 2022). "Using MR, we inferred a causal role of lower methylation and lower expression of CHRNA5 with increased risk for lung cancer." (PMID 33752734, 2021). "Our MR results further demonstrate that in humans, genetic variants in CHRNA5 affect smoking and lung cancer risk through effects on DNA methylation and gene expression of CHRNA5." (PMID 33752734, 2021). "Bidirectional MR revealed that the association of CHRNA5 with risk of lung cancer is causally influenced by both genetic and environment effects." (PMID 33752734, 2021). "CHRNA5, the gene that encodes the acetylcholine receptor subunit alpha 5, has been reported to be associated with tobacco addiction and lung cancer." (PMID 33752734, 2021). "The inferred causal relation between gene expression and lung cancer was further tested using cis eQTLs in lung tissue from GTEx as the instrumental variable, expression of CHRNA5 as the exposure, and lung cancer as the outcome." (PMID 33752734, 2021). "The genetic polymorphisms (rs2853669 in TERT, rs1052133 in OGG1, and rs16969968 in CHRNA5 genes) were shown to be strongly associated with the risk of lung cancer." (PMID 32257438, 2020). "We evaluated association of several SNPs in the CHRNA5/A3/B4 gene encoding nAChR subunit with lung cancer measuring frequencies of minor alleles and genotype distribution." (PMID 29416783, 2018). "On the other hand, only the CHRNA5 rs3841324 SNP has been investigated with respect to the possible relationship with lung cancer susceptibility." (PMID 25329654, 2014). "This is the first molecular epidemiologic study to investigate the association between CHRNA5 rs3841324, a susceptible variation for lung cancer, and susceptibility to smoking-associated cancer in addition to lung cancer." (PMID 25329654, 2014). "Based on the National Human Genome Research Institute (NHGRI) GWAS Catalog, SNPs in CHRNA5/A3/B4 are associated with overall lung cancer, lung ADC, and smoking; SNPs in CHRNB3 are associated with cigarettes smoked per day." (PMID 25233467, 2014). "The strongest impact on the risk of substance abuse and lung cancer is associated with variation in CHRNA5." (PMID 24303001, 2013). "Previously we found that variation in CYP2A6 and CHRNA5-CHRNA3-CHRNB4 combined to increase lung cancer risk in a case-control study in European American ever-smokers (n = 860)." (PMID 23591849, 2013). "Additional SNP associations were observed on 15q25.1 in genes previously associated with lung cancer, including a missense variant in CHRNA5 (rs16969968: OR = 1.60, 95% CI = 1.27-2.01, P = 5.9 × 10−5)." (PMID 23232035, 2012). "GWAS using several lung cancer populations have also demonstrated association between lung cancer susceptibility and the same or highly correlated variants in the CHRNA5-CHRNA3-CHRNB4 gene cluster." (PMID 22438940, 2012). "SNPs in the chromosome 15 CHRNA3/CHRNA5/LOC123688/IREB2 region have been shown to have associations with lung cancer and COPD unrelated to AAT deficiency." (PMID 22356581, 2012). "Individuals who do not carry the risk allele, however, may also be at increased risk for lung disease by virtue of smoking-related altered methylation of CHRNA5, which in turn increases lung cancer risk." (PMID 33752734, 2021). "This analysis revealed consistent causal effects of CHRNA5 on lung cancer." (PMID 33752734, 2021).